TNF (tumor necrosis factor)
Diseases named in the same sentence as TNF in open-access papers (continued):
Sharing a sentence is not in itself a finding about the gene and the disease.
coronary atherosclerosis (continued). "The results concerning the transcriptional activity of the genes of type I and II receptors of tumor necrosis factor alpha (TNFR1, TNFR2) were also surprising; they were the highest in the group with coronary atherosclerosis excluded in coronary angiography." (PMID 39684812, 2024). "MiR-155 was also reported to attenuate the formation of foam cells in coronary atherosclerosis and relieves the chronic inflammation by inhibiting calcium-regulated heat stable protein 1 (CARHSP1) and tumor necrosis factor alpha (TNF-α)." (PMID 34136547, 2021). "The present findings suggest that TNF-α has an impact on coronary atherosclerosis, but it does not correlate with the severity of CAD." (PMID 39091640, 2024). "We may speculate that TNFα and IL-6 may play a primary role in the promotion of coronary atherosclerosis, although the lack of a time-course observation in our experimental setting did not allow us to support this assumption with data." (PMID 39456434, 2024). "Plasma resistin levels were found to be correlated with markers of inflammation, such as IL-6 and TNF-α, and thus could predict coronary atherosclerosis in humans independent of CRP." (PMID 34209146, 2021). "Based on this observation, it is possible that the biological consequence of CRP- and TNF-α-induced PAPP-A expression in human PBMCs was enhanced IGF-I bioactivity mediated by PAPP-A proteolysis of IGFBP-4, thus contributing to the progression of both coronary atherosclerosis and restenosis." (PMID 22997483, 2012).
Huntington disease (35 papers, 2010 to 2025). Huntington disease (HD) is a rare neurodegenerative disorder of the central nervous system characterized by unwanted choreatic movements, behavioral and psychiatric disturbances and dementia. "On day 3 following lithium-pilocarpine administration (compared with controls), the majority of regulated signaling pathways were as follows: Huntington’s disease, tumor necrosis factor (TNF) signaling, tight junction, and nuclear factor (NF)-kappa B pathways." (PMID 36531133, 2022). "On day 3 following lithium-pilocarpine administration (compared with controls), the only indicated pathways were those relevant to Huntington’s disease, TNF signaling, NF-kappa B signaling, etc., however, there were no more than four proteins in each pathway." (PMID 36531133, 2022). "On day 3, pathways relevant to Huntington’s disease, and tumor necrosis factor signaling were most prevalent." (PMID 36531133, 2022). "We propose several possible scenarios for experimental studies initiated via the extra-cellular ligands TGFB1, FGF2 and TNF aiming at restoring the cellular homeostasis in Huntington's disease." (PMID 27924190, 2016). "Furthermore, the calcium channel blockers verapamil and diltiazem significantly downregulate quinolinic acid-induced TNF-α and IL-6 levels in a rat model of Huntington’s disease." (PMID 37435081, 2023). "TNF is upregulated in Huntington's disease (HD), like in PD and AD, but it is unknown whether TNF signaling contributes to neuronal degeneration in HD." (PMID 24824433, 2014). "We used in vivo gene delivery to test whether selective reduction of soluble TNF signaling could attenuate medium spiny neuron (MSN) degeneration in the YAC128 transgenic (TG) mouse model of Huntington's disease (HD)." (PMID 24824433, 2014). "To evaluate whether cytokines are altered in peripheral blood of rats transgenic for the human Huntington ́s disease mutation we investigated serum levels of GRO/KC, IL-1β, IL-13 and TNF-α at a symptomatic stage at 12 months of age." (PMID 20981129, 2010). "In an in vivo model, using 3‐nitropropionic acid (3‐NP) to induce Huntington's disease, CBG (10 mg·kg−1 per day i.p.)significantly attenuated the up‐regulation of COX‐2, iNOS, IL‐6, and TNF‐α." (PMID 32608035, 2020). "Essentially, abrogation of TNF-α and IL-6 alongside COX-2 downregulation mediated the neuroprotective effects of meloxicam in experimental LPS-evoked brain neuroinflammation, quinolinic acid-induced Huntington’s disease-like manifestations, and in a painful nerve root injury model." (PMID 37375795, 2023). "On the other hand, the pathway related to Huntington’s disease and hematopoietic cell lineage in the TBI + RP EVs and the thyroid hormone synthesis and tumor necrosis factor (TNF) signaling pathway in the TBI + NSS Evs were nominated as characteristic pathways in each EV." (PMID 37238707, 2023).
oral mucositis (35 papers, 2013 to 2026). Inflammation of the mucous membranes of any of the structures in the mouth. "Cytokines such as interleukin (IL)-1 beta (IL-1β), IL-6, IL-8, and tumor necrosis factor (TNF) have been linked to oral mucositis, and possibly xerostomia, during RT, manifested by elevated levels in saliva immediately after treatment in HNC patients." (PMID 36350483, 2022). "The primary damage of oral mucositis response describes an activation of transcription factors such as NF-κB leading to the production of pro-inflammatory cytokines such as TNF-α, IL-1β, and IL-6, which cause damage to both epithelium and connective tissue." (PMID 30274314, 2018). "As described in the literature, oral mucositis is associated with the activation of NF-κB and a subsequent upregulated expression of pro-inflammatory molecules, e.g. TNF α and IL-1/6." (PMID 29663036, 2018). "For example, in 5-fluorouracil (5FU)-induced oral mucositis in hamsters, AuNPs improved inflammation parameters, and decreased expression of genes encoding TGF-β, TNF-α, COX-2, IL-1β, NF-κB, and SMAD 2/3." (PMID 38082190, 2024). "Elevated TNF-α and IL-6 levels have been found in patients with severe radiation-induced oral mucositis as well." (PMID 39519149, 2024). "Studies have even found that TNF can serve as a monitoring marker for the severity of R/CIOM, where patients with higher levels of TNF tend to exhibit more severe oral mucositis." (PMID 39329977, 2024). "In a 5-FU-induced oral mucositis hamster model, TNF-α inhibitors were found to reduce the severity of oral mucositis." (PMID 36499758, 2022). "In oral mucositis, NF-κB is involved in the initial inflammatory damage to connective tissue by increasing the expression of pro-inflammatory cytokines, including TNF-a, MMPs, COX-2, TGF-B, and IL-1B." (PMID 33777752, 2021). "By reducing the expression of the NFKB/P65 gene and protein, these compounds reduce the levels of anti-inflammatory cytokines such as TNF-a and IL-6, and by the same mechanism, they can reduce ulcers and inflammation in oral mucositis." (PMID 33777752, 2021). "The proinflammatory cytokines, IL-1β and TNF-α, play an important role in the pathophysiology of oral mucositis." (PMID 32230975, 2020). "Grade 3/4 radiation-induced oral mucositis tends to be worse in the TPF + P group compared to the TNF + N group (31.9% vs. 21.2%, P = 0.071)." (PMID 33123269, 2020). "Early inflammation, as indicated by the expression of the inflammatory markers TNFα, NF-κB, and IL-1β, is an essential component of early radiogenic oral mucositis." (PMID 28258409, 2017). "It is well established that cytokines, in particular TNF-α and IL-1 β, play important roles in the pathophysiology of oral mucositis." (PMID 25478918, 2014). "Previous studies have confirmed significant positive effects of administrating such agents including amifostine and TNF-α inhibitors in prevention or amelioration of transplant-related complications like oral mucositis (OM) and acute GVHD." (PMID 24942646, 2014). "Evaluating oral pain at the same time point, they suggested that the local level of TNF-α is a more reliable indicator of oral mucositis severity." (PMID 24942646, 2014). "A study using an animal model of oral mucositis demonstrated that Atorvastatin significantly reduced TNF-α and IL-1β levels." (PMID 24130702, 2013). "Melatonin mitigates oral mucositis primarily by inhibiting NF-κB activation, thereby reducing pro-inflammatory cytokine expression (e.g., TNF-α, IL-1β) while also scavenging reactive oxygen species and enhancing antioxidant enzyme activity to protect and repair mucosal tissues." (PMID 40671993, 2025). "The initiation phase of oral mucositis starts with the damage by reactive oxygen species; then, NF-kB, TNF-α, IL-1β, and IL-6 carry the inflammation phase; immune cells cause the apoptosis of the epithelium and lead to the ulceration phase; eventually, the healing phase occurs." (PMID 37504247, 2023).
oral mucositis (continued). "Management of oral mucositis may include usage of benzydamine mouthwash due to its anti-inflammatory properties, which inhibit production of TNFα and IL-1β." (PMID 32260309, 2020). "Interestingly, amifostine prevented the immunoexpression of key inflammatory markers, such as TNF-α, IL-1β, and iNOS, confirming the anti-inflammatory effect of that drug and suggesting the potential applicability to manage oral mucositis." (PMID 30810625, 2019). "Consistently, the animals that received 5-FU followed by mechanical trauma of the cheek presented macroscopic and microscopic lesions accompanied by an inflammatory response with accumulation of TNF-α, IL-1β, iNOS, and reduced salivary rate, indicating the establishment of ongoing oral mucositis." (PMID 30810625, 2019). "This hypothesis is supported by the missing effect of specific TNFα inhibition with infliximab on oral mucositis, obtained in another study in the mouse tongue model." (PMID 28258409, 2017). "Although the mechanisms of chemotherapy-induced oral mucositis remain to be clarified, production of reactive oxygen species and proinflammatory cytokines such as TNF-α and IL-6 in the oral mucosa after exposure to high-dose chemotherapy is considered to be implicated in the pathogenesis." (PMID 27418192, 2016). "This positive effect of HPMC/GSNO on the healing phase of experimental oral mucositis was associated with reduced mucosa-inflammatory cell infiltration, decreased TNF-α levels and reduced immunostaining for iNOS and TNF-α in the cheek pouches of hamsters subjected to 5-FU-induced oral mucositis." (PMID 25478918, 2014). "For instance, in radiation-induced oral mucositis, the miR-200 family alleviates inflammation by suppressing cytokines, such as TGF-β, TNF-α and IL-1α." (PMID 40909958, 2025). "In an oral mucositis experimental model, administration of AZIL dramatically lowered TNF-α and IL-1β levels while boosting the levels of the anti-inflammatory cytokine IL-10." (PMID 37908315, 2023). "This product reduced the severity and duration of grade 3 oral mucositis, as indicated by a lower inflammatory profile (interleukin (IL)-1β, transforming growth factor (TGF)-β, and tumor necrosis factor (TNF)-α) in canine patients." (PMID 37444487, 2023). "All patients with oral mucositis received PBM 6 days/week and the outcome parameters were levels of TNF-α and IL-6 measured before, during, and after administration of PBM." (PMID 32260309, 2020). "The pro-inflammatory cytokines increased significantly in the animals with untreated oral mucositis (5-FU) compared to the PVP group: IL-1β (p < 0.001 vs. 5-FU) and TNF-α (p < 0.0001 vs. 5-FU)." (PMID 32230975, 2020). "For TNF-α, the unmethylated (hypomethylated) profile at CpG sites−245 and −239 was more frequent in patients who had oral mucositis during treatmentbut recovered and were not inflamed at the time of collection." (PMID 38747829, 2024). "TNF-α can modulate the expression of other cytokines such as IL-1β and IL-6 and affect the apoptosis and survival of other cells, hence it was postulated that TNF-α was important in the pathogenesis of oral mucositis." (PMID 36499758, 2022).
primary immunodeficiency (35 papers, 2008 to 2025). "In certain immune deficiency disorders, elevated TNF-α production has been demonstrated to be a mediator of some of the disease pathology." (PMID 19019236, 2008). "Given the epigenetic control over primary immunodeficiency and TNF/MAPK signaling pathway regulation, ChIP-qPCR was used to detect histone marker enrichment in CXCL10 and MECOM genes." (PMID 40805064, 2025). "It is mainly enriched in the PPAR signaling pathway, IL-17 signaling pathway, primary immunodeficiency, and TNF signaling pathway." (PMID 40164948, 2025). "KEGG analysis indicates that the genes were significantly enriched in Neutrophil extracellular trap formation, TNF signaling pathway, Cytokine-cytokine receptor interaction, and Primary immunodeficiency." (PMID 36536067, 2022). "Similarly, RA-related genes that interacted with CXCL16 were found to be significantly enriched with inflammation- and/or immune-related pathways, such as “Ferroptosis”, “Primary immunodeficiency” and “TNF signaling pathway” (p < 0.05, hypergeometric distribution model)." (PMID 40569958, 2025). "One was taking a TNF inhibitor and one had primary immunodeficiency post-HCST without full immune reconstitution." (PMID 38616263, 2024).
SARS-CoV infection (35 papers, 2006 to 2023). "There is other mechanism of infection related to SARS-CoV infection which is associated with high levels of cytokines, including interleukin (IL)-1β, IL-6, IL-12, interferon gamma (INFγ) and tumor necrosis factor-alpha (TNFα)." (PMID 33613024, 2021). "In the early stages of SARS-CoV infection, cytokine levels in the blood, such as Il-6, Il-8, and TNF-α, are rapidly elevated, the elevation of which is associated with the progression of lung invasion and injury." (PMID 32754600, 2020). "TNFα is a potent driver of leukocyte-mediated inflammation which in the case of normal SARS-CoV infection likely causes significant tissue damage." (PMID 27663205, 2016). "This study was to investigate the relationship between tumor necrosis factor (TNF)-α gene polymorphisms with the occurrence of SARS-CoV infection and its role in prognosis of patients with lung interstitial fibrosis and femoral head osteonecrosis." (PMID 18312678, 2008). "Under the SARS-CoV infection context, evidence has shown that single-nucleotide polymorphisms (SNPs) of the TNF promoter region (genotypes 1031CT/CC and 863) may represent risk factors in SARS." (PMID 34445140, 2021). "In order to explore more host factors influencing the occurrence of SARS-CoV infection, we studied the polymorphisms of TNF-α gene at the promoter region, which had been ascribed to polymorphisms within the regulatory regions or signal sequences of cytokine genes." (PMID 18312678, 2008). "In order to explore more host factor influence the occurrence of SARS-CoV infection, we studied the polymorphisms of TNF-α gene at the promoter region, which have been ascribed to polymorphisms within the regulatory regions or signal sequences of cytokine genes." (PMID 18312678, 2008). "We examined whether polymorphisms of IFN-γ,TNF-α and IL-10 affect the susceptibility to and outcome of severe acute respiratory syndrome (SARS)." (PMID 16672072, 2006). "In animal models of SARS-CoV infection, TNF activity neutralization provides protection against SARS-CoV morbidity and mortality." (PMID 37569398, 2023). "High levels of proinflammatory cytokines such as tumor necrosis factor-alpha (TNF-α) and interleukins are produced readily by innate immune cells to fight Severe Acute Respiratory Syndrome-Coronavirus-2 (SARS-CoV-2) infections." (PMID 37047115, 2023). "In SARS-CoV infections, it is worth noting that TNF-α-induced inflammation can increase the pathogenesis and preassembly of infective virus particles; therefore, TNF-α inhibitors are recommended to reduce severe disease outcomes." (PMID 37047115, 2023). "Interleukin (IL)-4 and IFN-γ/tumor necrosis factor (TNF)-α reduced Ace2 expression in Vero E6 cells, resulting in decreased SARS-CoV infection; thus, genetic regulation of ACE2 via cytokines appears to be cell type-dependent." (PMID 36405683, 2022). "Previously, higher expression of pro-inflammatory cytokine levels (IFN-α, TNF, IL-6, IL-8, IL-10, and IP-10) were described in monocyte-derived macrophages in SARS-CoV infections." (PMID 34539631, 2021). "Under the influence of chemokines (CCL3, CCL4, CCL5, CCL8), TH1 cells are recruited to the site of infection and are distinguished by the secretion of IL-2, IFN-γ, IL-12, and TNF-α as the main effector cytokines during SARS-CoV infections." (PMID 33335518, 2020). "Another study showed that the coding gene for hydroxysteroid 17-beta dehydrogenase 2 (HSD17B2) was downregulated in SARS-CoV infection, which is a consequence of stimulation of IL-1, IL-6, and TNFα as well as induction of inflammation." (PMID 32754004, 2020). "Intriguingly, both SARS-CoV infection and concomitant TNF-α secretion were significantly attenuated not only by knock-down of ADAM17/TACE expression by siRNA but also by deletion of the ACE2 cytoplasmic tail which is responsible for ADAM17/TACE activation." (PMID 32708755, 2020).
SARS-CoV infection (continued). "The results presented here suggest the role of Kepi in the host response to SARS-CoV, as well as inflammatory activity driving pathogenesis through TNFα signaling in SARS-CoV infections." (PMID 27663205, 2016). "We found that there was a weak protective effect of CT genotype at -204 locus of TNF-α gene against SARS-CoV infection." (PMID 18312678, 2008). "The rationale of its utilization is the up-regulation of tumor necrosis factor-α (TNF-α) demonstrated in murine models of severe acute respiratory syndrome (SARS), and the elevated levels of the cytokine detected in a subgroup of patients with severe disease and cytokine storm." (PMID 33947420, 2021). "Previous studies have confirmed the role of TNF-α in promoting the pathogenesis of SARS-CoV infection through its receptors and suggested that the inhibition of TNF-α signaling might be leveraged as a treatment strategy." (PMID 33424804, 2020). "In this paper, we aimed to study whether polymorphisms in TNF-α promoter region were associated with SARS-CoV infection, development, and progression of interstitial lung fibrosis and femoral head necrosis in cure SARS patients." (PMID 18312678, 2008). "Considering that IFN may contribute to the tissue degradative effects of TNF-α already induced by SARS-CoV infection, the problem is to polarize the mouse immune system to a Th2 inflammatory response, with undesired consequences to patient recovery from SARS-CoV infection when treated with an IFN." (PMID 33426096, 2020). "Second, our work highlights the critical balance involved in regulating inflammatory machinery during SARS-CoV infection, and suggests that inhibition of TNFα or PP1 signaling may represent viable avenues for future investigations into effective pharmaceutical therapies." (PMID 27663205, 2016). "Abnormalities in the production levels of several cytokines such as IL-1, IL-2, IL-4, IL-6, IL-8, IL-10, IFN-γ, TNF-α and TGF -β1 were detected in patients with SARS-CoV infection." (PMID 32917282, 2020). "During the process of SARS-CoV infection, there was a cytokine storm in patients including IL-1, IL-2, IL-4, IL-6, IL-8, IL-10, IFN-γ, TNF-α and TGF-β1." (PMID 18312678, 2008). "SNPs of TNF-α gene of promoter region may not associate with SARS-CoV infection." (PMID 18312678, 2008). "TNF and IFN-γ are among the main produced cytokines during SARS-CoV infection." (PMID 37494451, 2023). "EBN also attenuated the surge in pro-inflammatory cytokines and chemokines such as TNF-α, CCL-2, NF-κβ, NO, IL-6, and increased IFN-γ, which are dysregulated in severe forms of IAV, and SARS-CoV infections." (PMID 34025406, 2021). "Our studies indicate that protection from SARS-CoV infection correlates with MyD88-dependent induction of IL1-β, TNF-α, IL-6, MCP-1, MIP-1α, and RANTES at early times post infection and many of these cytokines/chemokines were upregulated in human SARS-CoV cases." (PMID 19079579, 2008).